FAAH (fatty acid amide hydrolase)
Diseases named in the same sentence as FAAH in open-access papers (continued):
Sharing a sentence is not in itself a finding about the gene and the disease.
colitis (14 papers, 2012 to 2024). Inflammation of the colon. "In fact, FAAH inhibition and CB receptor activation have shown efficacy in mouse models of colitis and FAAH knockout mice are less susceptible to experimentally induced colitis compared to wild-type mice." (PMID 37884682, 2024). "We examined how genetic variants of FAAH could influence the peripheral and neuroinflammatory response in colitis in a recently developed mouse model expressing the human SNP of FAAH." (PMID 34916909, 2021). "5-ASA, through PPARα receptor, and glucocorticoids, through acylethenolamide producing/degrading enzymes, reduces colitis-associated inflammation suggesting PPARα agonists or FAAH/NAAA inhibitors as potential drugs for the treatment of inflammatory bowel diseases in human." (PMID 22662201, 2012). "NAAA has limited reported connections to IBD, but studies found decreased PPAR, PPAR, and NAAA, with increased FAAH and iNOS, in colitis mucosa." (PMID 38893707, 2024). "Therapeutically, both exogenous administration of cannabis and preventing endocannabinoid degradation by inhibiting FAAH have been shown to reduce colitis." (PMID 37884682, 2024). "In the same colitis model, the inhibition of FAAH with URB597 increased the concentration of AEA in the colon and reduced its damage, improved survival rates, and preserved BBB integrity." (PMID 38247868, 2024). "Open arm time was reduced with TNBS-induced colitis and increased with administration of the FAAH inhibitor." (PMID 33452437, 2021). "Given that FAAH activity was broadly increased following colitis, we opted to perform a central inhibition of FAAH to determine the impact of widespread central elevations in AEA signaling." (PMID 33452437, 2021). "Colitis also resulted in an increase in FAAH-mediated hydrolysis of AEA across corticolimbic structures important for the regulation of affective behavior." (PMID 33452437, 2021). "That said, the magnitude of reduction of colitis damage in the current study from central FAAH inhibition was relatively minor." (PMID 33452437, 2021). "An unexpected finding of this study was that acute central inhibition of FAAH reduced the severity of colitis." (PMID 33452437, 2021). "Together these results indicate that central FAAH inhibition reverses colitis-induced suppression of open arm time and reduces macroscopic colonic tissue damage score." (PMID 33452437, 2021). "Many of the colitis-induced cytokines that we found to be influenced by the FAAH SNP (e.g., IL-2, LIF, MCP-1, and TNF), have been found to be regulated by FAAH inhibition in other studies." (PMID 34916909, 2021). "We only measure one time point, and it is possible that without a time course analysis, we are missing subtle dynamics as to the effects of both colitis, FAAH genotype and their combination on cytokine expression levels, both peripherally and centrally." (PMID 34916909, 2021). "In summary, in mice with acute colitis, increased plasma and amygdala cytokine levels are regulated by the activity of FAAH." (PMID 34916909, 2021). "For instance, treatment with FAAH antagonists or genetic ablation of FAAH protected against colitis inflammation." (PMID 22662201, 2012). "Gene expression analysis indicated a decrease of PPARα, PPARγ and NAAA, and an increase of FAAH and iNOS in the active colitis mucosa." (PMID 22662201, 2012). "There were effects of both colitis and the FAAH SNP on amygdala cytokine and chemokine levels." (PMID 34916909, 2021). "In contrast, chemical-induced colitis increases the percentage of CB1R-expressing myenteric neurons, while the cannabinoid receptor agonist HU210 or the genetic ablation of FAAH protects from the chemical-induced colitis." (PMID 35634468, 2022). "The finding that CRF-R1 activity mediates the colitis-induced reduction in AEA content broadens previous work indicating that CRF and FAAH exhibit an intricate relationship in the regulation of affective behavior." (PMID 33452437, 2021).
colitis (continued). "The inhibition of cannabinoids degrading FAAH and MAGL enzymes was shown to be protective against colitis induced by dextran sulfate sodium (DSS) and trinitrobenzene sulfonic acid (TNBS)." (PMID 34503163, 2021). "A dual FAAH and COX inhibitor has been shown to increase AEA and PEA levels, reducing features of colitis in mice." (PMID 32372912, 2020). "Moreover, treatment of wild-type mice with cannabinoid antagonist SR141716A mimicked the CB1-deficient phenotype, and administration of CB1 receptor agonist HU210, or genetic inhibition of FAAH, protected against DNBS-induced colitis in the mice." (PMID 34503163, 2021). "Additionally, inhibition of FAAH decreased the accumulation of inflammatory cytokines and inhibited leukocyte proliferation in DNBS-experimental colitis." (PMID 34503163, 2021). "However, both FAAH expression and levels of AEA have been reported to be decreased or increased in colitis from different studies, pointing towards the need for further studies to fully address the role of ECS in the modulation of intestinal inflammation." (PMID 28990365, 2018). "In the amygdala, the mutant A allele led to lower levels of IL-1α, IL-9, macrophage inflammatory protein (MIP)-1β, and MIP-2 independent of colitis—providing additional understanding of how FAAH may serve as a regulator of inflammatory responses in the brain." (PMID 34916909, 2021). "However, it is unclear why reducing FAAH activity does not attenuate colitis-induced increases in IL-6, given what others have shown." (PMID 34916909, 2021).
cognitive deficits (13 papers, 2019 to 2025). "We then hypothesized that the complete knockout of FAAH would rescue hyperarousal and cognitive impairment in PS19 mice." (PMID 38543105, 2024). "Furthermore, our findings suggest that using FAAH/MAGL inhibitors for the prevention of cognitive impairment should be sex specific." (PMID 37700370, 2023). "It points to FAAH inhibition as a viable pharmacological approach to treat numerous central nervous system disorders including neurodegenerative diseases, mood disorders, and cognitive deficits, among others." (PMID 36979699, 2023). "In contrast, when AEA levels are increased via the pharmacological inhibition of the FAAH or by genetic FAAH deletion, cognitive abilities are improved even if studies reporting cognitive impairments after FAAH inhibition are also evident." (PMID 31379568, 2019). "The FAAH and MAGL inhibitors alone or in combination seem to produce neuroprotection by reversing cognitive deficits along with Aβ-induced neuroinflammation, oxidative responses, and neuronal death, delaying AD progression." (PMID 38612861, 2024). "Moreover, inhibitors targeting fatty acid amide hydrolase (FAAH) and monoacylglycerol lipase (MAGL) have demonstrated efficacy in reversing cognitive impairments and alleviating neuroinflammation in mouse models of AD." (PMID 40508160, 2025).
schizophrenia (13 papers, 2014 to 2025). A major psychotic disorder characterized by abnormalities in the perception or expression of reality. "More recently, an association between the variant FAAH p.Pro129Thr with substance use was found in individuals with schizophrenia." (PMID 35563156, 2022). "CBD also inhibits rodent fatty acid amide hydrolase (FAAH), resulting in increased levels of anandamide, which is associated with decreased clinical symptoms of schizophrenia." (PMID 38716117, 2024). "More work is needed to investigate role of the eCB system in schizophrenia and cannabis-induced experiences, as previous research has shown that the FAAH rs324420 SNP is involved in behavioural manifestations of cannabis addiction." (PMID 32398646, 2020). "In the context of the results presented in our manuscript associated with cognitive-related schizophrenia symptoms, the few literature data available describe the role of other FAAH or MAGL inhibitors in the control/modulation of schizophrenia symptoms in experimental animal models." (PMID 37511157, 2023). "The association of some FAAH or NAPDE-PLD polymorphisms with schizophrenia was studied, but no significant results were obtained." (PMID 35563156, 2022). "Interestingly, decreased FAAH mRNA levels were significantly correlated with clinical remission in patients with schizophrenia." (PMID 35563156, 2022). "Therefore, this information can be used by medicinal chemists to design novel, more potent and selective FAAH inhibitors to treat patients suffering from a number of diseases, e.g., Parkinson’s disease or schizophrenia." (PMID 34204026, 2021). "Specifically, we hypothesize that lower brain FAAH activity will predict worse cognitive performance, particularly in cognitive domains such as attention and executive functioning, typically affected in schizophrenia." (PMID 39729518, 2025). "Moreover, the FAAH rs324420 SNP has also not been associated with diagnosis in the latest schizophrenia GWAS30." (PMID 32398646, 2020). "We evaluated that the direct influence of ECS, using FAAH (URB 597) and MAGL (JZL 184) inhibitors, on the schizophrenia-like effects in mice." (PMID 31004320, 2019). "Naturally, the third component of the ECS system, i.e., endocannabinoids and enzymes responsible for the metabolism of endocannabinoids (FAAH and MAGL), is also important in the context of schizophrenia-like effects." (PMID 31004320, 2019). "Our results allow evaluating of the possible relationship between ECS and positive or cognitive symptoms of schizophrenia, focusing on the indirect modulation of ECS functioning, using FAAH or MAGL inhibitors." (PMID 31004320, 2019). "However, a new and still poorly researched strategy is the assessment of the FAAH and MAGL inhibitors on the course of schizophrenia symptoms." (PMID 37511157, 2023). "Although URB 597 as a FAAH inhibitor has been studied most intensively, its precise influence on memory or other schizophrenia-like effects has not been fully characterized." (PMID 31004320, 2019). "The usefulness of FAAH inhibitors remains uncertain; thus, recent studies have also proposed that MAGL inhibitors may be novel modulators for symptoms of schizophrenia." (PMID 31004320, 2019). "An [11C]CURB PET study that investigated fatty acid amide hydrolase (FAAH), an enzyme of the endocannabinoid system that degrades anandamide and thereby indirectly regulates cannabinoid receptor signaling, examined 16 males with ASPD and 16 male control participants (five with schizophrenia)." (PMID 37884552, 2023).
anxiety disorder (12 papers, 2015 to 2022). A category of psychiatric disorders which are characterized by anxious feelings or fear often accompanied by physical symptoms associated with anxiety. "In line with this, polymorphisms in the gene encoding for FAAH (FAAH), have been linked to an increased risk of depressive and anxiety disorders." (PMID 30959794, 2019). "Interestingly, BLA habituation in response to emotional faces, an indicator of fear extinction, was the most reduced in participants carrying genetic polymorphisms associated with enhanced CRF and FAAH signaling, an effect which mediated increased risk for anxiety disorders." (PMID 30239920, 2018). "With the investigation of FAAH inhibitors for anxiety disorders and anxious endophenotypes, our data support the careful testing of these pharmacological agents in personality disorders with high neuroticism." (PMID 35064143, 2022). "Inhibition of FAAH has long been proposed to have potential as a treatment for anxiety disorders based on effects in preclinical models but evidence of an effect in clinical disorders has not been reported to date." (PMID 33070154, 2021). "In the current study, we tested the association between polymorphisms of the CNR1, CNR2, and FAAH genes and response to CBT in children and adolescents with an anxiety disorder diagnosis." (PMID 27346075, 2017). "Given the potential role of the ECB system in fear extinction and the maintenance of extinction memories, this study investigated whether genetic variation in the CNR1, CNR2, and FAAH genes was associated with response to CBT in children and adolescents with an anxiety disorder." (PMID 27346075, 2017). "We investigated the relationship between variation in the CNR1, CNR2, and FAAH genes and change in primary anxiety disorder severity between pre‐ and post‐treatment and during the follow‐up period in the full sample and a subset with fear‐based anxiety disorder diagnoses." (PMID 27346075, 2017). "In the management of anxiety disorders, drug development strategies have left apart the direct activation of type-1 cannabinoid receptors to indirectly enhance eCB signalling through the inhibition of eCB deactivation, that is, the inhibition of the fatty acid amide hydrolase (FAAH) enzyme." (PMID 26360704, 2015). "These comorbidities may not explain our findings, but we do not rule out the possibility that FAAH may be dysregulated in anxiety disorders." (PMID 32521537, 2020).
alcohol use disorder (9 papers, 2010 to 2025). "Interestingly, carriers of the FAAH rs324420 A allele have been significantly associated with a higher risk of alcohol use disorder (AUD) and substance use disorders, including cannabis dependence." (PMID 40431452, 2025). "Moreover, negative correlations between plasma levels of N-acylethanolamines and FAAH levels in the human brain using the FAAH tracer [11C]CURB in patients with alcohol use disorder has been shown supporting the suggestion of peripheral endocannabinoids as a proxy for central endocannabinoid levels." (PMID 38773316, 2024). "However, the largest GWAS to date on alcohol use phenotypes, including alcohol use disorder, problematic alcohol use, and drinks per week, have also not found genome-wide associations with FAAH." (PMID 37761966, 2023). "Specifically, we found that BPD participants who were medication-free, nonsubstance using, nonsmoking, had no alcohol use disorder, were not experiencing an MDE, but were still engaging in non-suicidal self injury, had higher FAAH levels in the PFC compared with healthy controls." (PMID 32521537, 2020).
Miscarriage (9 papers, 2009 to 2022). A pregnancy that ends at a stage in which the fetus is incapable of surviving on its own, defined as the spontaneous loss of a fetus before the 22th week of pregnancy. "Elevated plasma AEA in early pregnancy (<8 weeks) and lower peripheral lymphocyte expression of FAAH has been associated with miscarriage, and the CB1-knock out mouse has elevated corticotrophin-releasing hormone (CRH) and spontaneous preterm labour." (PMID 31052173, 2019). "Furthermore, FAAH activity and protein levels were significantly lower in the blood lymphocytes of in vitro fertilization-embryo transfer patients who experienced miscarriages compared to those who had become pregnant." (PMID 35743292, 2022). "The examination of placentae from woman either undergoing elective abortion or being affected by spontaneous miscarriage revealed decreased FAAH protein levels between 9 and 12 weeks of gestation in samples of spontaneous miscarriage compared with uncomplicated early pregnancy samples." (PMID 35743292, 2022). "Additionally, high levels of plasma AEA in early pregnancy or low fatty acid amide hydrolase (FAAH) levels and activities have been shown to be associated with miscarriage." (PMID 19860893, 2009). "This is consistent with earlier reports, where strong immunopositivity for CB1 was found in trophoblast cells of placental samples of spontaneous miscarriage, although we did not detect lower FAAH signal in syncytiotrophoblasts as formerly reported." (PMID 25444073, 2014). "Comparison of the CB1, CB2, FAAH and NAPE-PLD staining patterns in tissues from medical terminations and spontaneous miscarriages showed that CB1 expression in the trophoblast layer decreased in both types of tissue when compared to that from surgical terminations." (PMID 22126420, 2011). "Comparison of the CB1, CB2, FAAH and NAPE-PLD staining patterns of medical terminations and spontaneous miscarriages indicated that CB1 expression in the decidua increased in individual cells of the medical terminations, but decreased in the spontaneous miscarriage group." (PMID 22126420, 2011).
Parkinson disease (9 papers, 2014 to 2025). A progressive degenerative disorder of the central nervous system characterized by loss of dopamine producing neurons in the substantia nigra and the presence of Lewy bodies in the substantia nigra and locus coeruleus. "Fatty acid amide hydrolase (FAAH) inhibitors and cannabinoid CB1 receptor antagonists have also been shown to alleviate Parkinson’s symptoms." (PMID 40283681, 2025). "URB597-induced FAAH inactivation significantly elevated levels of AEA, OEA, and PEA in the midbrain of mice with parkinsonism." (PMID 39104613, 2024). "Evidence from preclinical models highlights that modulating specific eCBS targets—such as CB1, CB2, FAAH, and MAGL—can attenuate drug-induced neurotoxicity and ameliorate neuropathological features of Alzheimer’s, Parkinson’s, Huntington’s, and motor neuron diseases." (PMID 41373784, 2025). "Further, MAGL inhibitors increased glial-derived neurotrophic factors and prevented neurodegeneration in a mouse model of Parkinson’s disease, but FAAH inhibition did not." (PMID 31695165, 2020).
posttraumatic stress disorder (9 papers, 2018 to 2026). "The FAAH rs2295633 polymorphism also has been associated with posttraumatic stress disorder." (PMID 34572359, 2021). "In the clinical trial with BIA-10-2474, a fatty acid amide hydrolase (FAAH)-inhibitor in development for diseases in which elevated endocannabinoid tone might be beneficial such as pain, glaucoma and post-traumatic stress disorder, several subjects developed neurological damage and one subject died." (PMID 36859342, 2023).
psychosis (8 papers, 2020 to 2025). "The aim of this study was to evaluate group differences in brain fatty acid amid hydrolase (FAAH), an endocannabinoid enzyme between first-episode psychosis (FEP), individuals with clinical high risk (CHR) for psychosis and healthy controls (HCs)." (PMID 39729518, 2025). "They demonstrated a positive association between FAAH activity (in eight different brain regions, including the ACC) and Glx concentration in the hippocampus of patients with psychotic disorders (n = 18) and HC (n = 19)." (PMID 38389452, 2024). "In support of this theory, a recent study found that the levels of fatty acid amide hydrolase (FAAH), the enzyme which metabolises anandamide and other related ligands, were inversely correlated with severity of psychotic symptoms in patients with psychosis." (PMID 34255100, 2022). "Interestingly, both dopamine receptor D2 and FAAH genotypes appear to modulate the effect of cannabis use on the development of psychosis, but these initial findings need to be replicated." (PMID 32059350, 2020). "In addition, such a study also reported increased FAAH levels during psychosis." (PMID 38404644, 2024). "Therefore, how the FAAH genotype and anandamide play a role in psychosis is still being debated." (PMID 32398646, 2020). "Since then, there have not been any studies with FAAH inhibitors in patients with psychosis, though one has been evaluated in otherwise healthy volunteers with cannabis dependence." (PMID 34255100, 2022).